IL1A (interleukin 1 alpha)
Diseases named in the same sentence as IL1A in open-access papers (continued):
Sharing a sentence is not in itself a finding about the gene and the disease.
tumor (continued). "In gastric cancer cells, N-myc downstream regulated gene 1 (NDRG1) increased IL-1α expression, which was then capable of driving tumor angiogenesis via a c-JUN N-terminal kinase (JNK)/AP-1 dependent pathway." (PMID 31293586, 2019). "Recently, in vivo treatment with anakinra using a PDAC orthotopic nude mouse model reduced tumor growth by inhibiting IL-1α induced NF-κB activity." (PMID 30760333, 2019). "IL-1a increased PD-L1 protein expression by ≥5 MFI in 6 of 14 tumor cell lines tested; notably, the effect of combining IL-1a with IFN-g was more than additive in 12 of 14 tumor cell lines, suggesting the cooperation of distinct signaling pathways." (PMID 31730010, 2019). "In contrast to IL‐1α and IL‐1β, which promote tumor progression through inflammation, IL‐1RA possesses a tumor‐suppressing effect by blocking the binding of IL‐1 to its target receptor." (PMID 31102307, 2019). "Here we show that IL-1α and IL-1β derived from tumor cells and tumor cell-conditioned macrophages is key for TSLP production by CAFs and blockade of IL-1 in vivo significantly reduced TSLP expression in the tumor." (PMID 30760333, 2019). "For example, breast cancer cells have been shown to recruit tumor-infiltrating myeloid cells via the cytokines interleukin (IL)-1α and t thymic stromal lymphopoietin (TSLP) to maintain their survival." (PMID 31416487, 2019). "Only 4 tumors had cytoplasmic only staining highlighting the importance of nuclear IL-1α (i.e., pro-IL-1α and/or IL-1α propiece (ppIL-1α)) in tumor cells." (PMID 31320902, 2019). "Several studies have showed that IL-1α contributes to tumour invasion, tumour proliferation, tumour metastases and interaction between the host immune system and malignant tumour cells." (PMID 30819119, 2019). "IL-1α production is a very early step in the sterile inflammatory response at the center of the malignant phenotype that drives angiogenesis, tumor stromal remodeling, tumor invasiveness, metastasis, and cachexia." (PMID 31182982, 2019). "These included inflammatory mediators related to protection against bacterial infection (Il1α, Tlr4, Lyz2, Mpo), all of which increased in brains of tumor-bearing mice relative to tumor-free controls during the dark phase only." (PMID 31019214, 2019). "In contrast, STAT3 knockdown in Monos reduced IL-10-induced PD-L1 protein expression, and p65 knockdown in tumor cells reduced IL-1a-induced PD-L1 expression." (PMID 31730010, 2019). "To investigate the selective effects of IL-1a and IL-27 on certain tumor cell lines, we quantified mRNA expression for the subunits of the IL-1a (IL1R1, IL1RAP) and IL-27 receptors (IL27RA, IL6ST)." (PMID 31730010, 2019). "In the present study, we report that tumor-derived IL-1α and IL-1β exert a primary role in driving TSLP secretion by CAF and that in vivo treatment with anakinra significantly reduces TSLP expression in the tumor." (PMID 30760333, 2019). "The IL-1α-NP formulation as a single agent also triggered tumor regression, although in only 6 of the 10 mice in this treatment group, which explains the non-significance of this treatment group on average compared to the control (EMP-NP)-treated group." (PMID 30890189, 2019). "Cytokines regulating PD-L1 expression, including IFN-g, IL-1a, IL-10, IL-27 and IL-32 g, signal through diverse transcription factors and have variable effects on tumor cells and Monos." (PMID 31730010, 2019). "The study of IL-1α is few, but it is also involved in tumor progression and metastasis, which can activate NF-κB and promote tumor growth." (PMID 31832112, 2019). "IL-1α-NPs were observed to be a relatively safe and effective option for IL-1α delivery and the anti-tumor activity of the combination of cetuximab and IL-1α-NP was T-cell dependent." (PMID 30890189, 2019). "Both IL-1a and IL-27 independently and significantly enhanced or induced PD-L1 protein expression on some cultured tumor cell lines, and further increased IFN-g-induced PD-L1 expression in some cases." (PMID 31730010, 2019).
tumor (continued). "Using the same 14 tumor cell lines that were assessed for the effects of IL-1a and IL-27 on PD-L1 expression as shown in Fig3a and b, respectively, we tested the effects of these cytokines on transcription factor activation." (PMID 31730010, 2019). "Nevertheless, in the current work, elevated brain Il1α and Il1β gene expression negatively predicted open field locomotion in all mice exposed to a tumor (combined tumor-bearing and -resected groups)." (PMID 31019214, 2019). "In our previous study, we demonstrated that the release of IL-1α from lung tumor-associated plasmacytoid dendritic cells was AIM2 inflammasome dependent and promoted tumor cell proliferation in the lung." (PMID 29675024, 2018). "We also found that residual tumor-promoting activity in skin of TNF−/− mice was induced by IL-1α and IL-1β gene expression." (PMID 30341686, 2018). "IL-1α/β are important components of the tumor microenvironment that stimulate tumor invasiveness and angiogenesis." (PMID 29445180, 2018). "Following CDDP administration in A375-bearing mice, the intratumour injection of neutralisation antibodies targeting the SASP factors IL-1α or IL-8 evidently delayed tumour growth." (PMID 29449532, 2018). "A recent report demonstrated that PDT-generated tumor cell lysate induces IL-1α, IL-1β, and IL-6 secretion from DCs suggesting that PDT-induced immune enhancement is due to DCs activation." (PMID 30680248, 2018). "In contrast, STAT3 knockdown in Monos reduced IL-10-induced PD-L1 protein expression, and p65 knockdown in tumor lines reduced IL-1a-induced PD-L1 expression." (PMID 30400822, 2018). "The mTOR inhibitor, rapamycin, results in direct inhibition of IL-1α synthesis (and consequently IL-6 secretion) which successfully prevented the tumor-promoting effects of senescent fibroblasts." (PMID 29868482, 2018). "RNA sequence analysis of myeloid-driven tumorigenic BPH-TW cells revealed increased expression of IL-1α and its target genes CXCL1 and CXCL8. shRNA knockdown of IL-1α in the transformed BPH-TW tumor cells resulted in decreased tumor growth." (PMID 29502208, 2018). "The results imply an active role of SASP factors in tumour microenvironment and further suggest that IL-1α and IL-8 are the key SASP factors promoting the growth of NS cells." (PMID 29449532, 2018). "The mean tumour weight decreased from 1.6 g in vehicle-treated mice to 0.97 and 0.94 g in anti-IL-1α-treated and anti-IL-8-treated mice, respectively." (PMID 29449532, 2018). "RNA sequencing identified the IL-1α pathway as a potential molecular mechanism responsible for tumor promotion by TAMC." (PMID 29502208, 2018). "Our data indicate that when SNAIL1 expression is activated in tumor cells, they produce less pro-inflammatory cytokines IL1α and TNFα and M1-like stimulating GM-CSF." (PMID 29593211, 2018). "NF-κB plays a pivotal role in linking chronic inflammation to cancer development through its ability to upregulate several inflammatory and tumor promoting cytokines such as IL-6, IL-1α, and TNF-α, as well as survival genes such as BCL2 and BCLXL." (PMID 29772687, 2018). "At three and 6 days following the CDDP injection in tumour-bearing mice, the IL-8 or IL-1α antibody was intratumour injected twice, independently." (PMID 29449532, 2018). "KSHV-infected monocytes produce a general proinflammatory response similar to the KS tumor microenvironment cytokines with enrichment of IL-1α, IL-1β, and IL-6 compared to uninfected control cells." (PMID 29018115, 2017).
tumor (continued). "IL-1α is found in tumour cell membranes and in intracellular locations, and is produced in larger amounts than IL-1β in highly metastatic tumours." (PMID 28381274, 2017). "IL-1α, as an important proinflammatory cytokine in the tumor microenvironment, can regulate tumor progression by increasing tumor growth, angiogenesis, and invasiveness." (PMID 29162930, 2017). "This is probably due to the low levels of both membrane and soluble TRAIL basally expressed by pIL6-TRAIL+-GFP+-UC-MSCs, since the transcription of TRAIL is reinforced by both IL-1α and IL-1β usually abundant within the tumor sites." (PMID 28962646, 2017). "Not only does IL-1B appear positively correlated with MAP17 in all tumors, other interleukins including IL-15, IL-18, IL-1A, IL-32 and IL-7 and interleukin receptors including IL-10RB, IL-17RC and IL-2RG appear in at least three of the tumor types." (PMID 29228712, 2017). "Neoplastic cells and tumor-associated macrophages (TAM) secrete IL-6, CSF-1, IL-10, TGF-β, TNF-α, IL-1α, angiogenic and lymphangiogenic growth factors that promote tumor development." (PMID 28830415, 2017). "In vivo growth of the T-ALL cells overexpressing the propiece IL-1α were also enhanced compared to the control cells in two murine tumor models." (PMID 28152513, 2017). "Strikingly, efficacious tumour immunosurveillance due to tumour-specific CD4 + T cells was consistently related to increased local concentrations of both proinflammatory (IL-6, IL-1α, and IL-1β) and Th1-associated cytokines (IL-2, IL-12, and IFN-γ)." (PMID 29089667, 2017). "MABp1 targets and binds to IL-1α, preventing IL-1α-mediated tumor growth, metastasis, and invasiveness." (PMID 27429614, 2016). "IL-1α is a highly proinflammatory cytokine, abundantly present in the tumor microenvironment, where it is released from various stromal cells as well as from carcinoma cells." (PMID 27473228, 2016). "The data show that TGFβ signaling suppressed IL-1α-mediated stellate cell-induced carcinoma cell migration, indicating that TGFβ inhibits tumor promoting effects of human pancreatic stellate cells." (PMID 27473228, 2016). "Taken together these data imply that lung tumor lesions are populated by macrophages which pro-tumor activity is regulated by the activation of the NLRP3 inflammasome that leads to the release of IL-1α and IL-1β in a caspase-11/caspase-1-dependent manner." (PMID 27528423, 2016). "Acting via its receptor IL-1R1, which belongs to the interleukin-1 receptor/Toll-like receptor superfamily, IL-1α exerts multiple effects in the tumor stroma, several of which are tumor-promoting." (PMID 27473228, 2016). "The expansion and activation of MDSCs is regulated by several factors (e.g. IL-4, IL-13, IL-1α, INFγ and GM-CSF) that are released by activated macrophages and T cells, tumor cells, tumor stromal cells, and by pathogen-infected cells." (PMID 27191744, 2016). "αCD40-induced changes in tumour inflammatory mediators IL-1α, RANTES (CCL5) and GM-CSF (CSF2) at the mRNA level did not translate into significant increases in protein expression (data not shown)." (PMID 26918344, 2016). "The IL-1α-driven inflammatory activation of lymphangiogenesis seems to provide a tumor microenvironment favorable for LN metastasis of lung cancer cells through crosstalk with macrophages." (PMID 28036019, 2016). "Since IL-1α plays an important role in immune and inflammatory responses, we thus further explored the roles of IL-1α 3′ UTR rs3783553 in recurrence of SCCOP patients stratified by tumor HPV16 status." (PMID 27121322, 2016). "Taken together these data imply that lung tumor lesions are populated by macrophages which pro-tumor activity is regulated by the activation of the NLRP3 inflammasome that leads to the release of IL-1α and IL-1β." (PMID 27528423, 2016). "IL-1α has previously been shown to activate PSCs and induce inflammatory responses in the tumor stroma." (PMID 27473228, 2016).
tumor (continued). "It was shown that the inflammatory tumorigenic microenvironment is derived from IL-1β secreted from the myeloid cells around the tumor, and the IL-1α secreted from the tumor cells accompanied with hypoxia, necrosis, or DNA damage." (PMID 28083070, 2016). "It has been demonstrated that IL-1α/β produced by tumor cells can augment capacity of MSCs-derived TAFs to suppress proliferation and function of T lymphocytes." (PMID 27630452, 2016). "In conclusion, our data imply lung tumor lesions are populated by macrophages which pro-tumor activity is regulated by the activation of the NLRP3 inflammasome that leads to the release of IL-1α and IL-1β in a caspase-11/caspase-1-dependent manner." (PMID 27528423, 2016). "IL-1α mRNA and protein levels were determined in tumor samples and cancer cell lines using RT-PCR and ELISA." (PMID 26460957, 2015). "We then examined the influence of IL-1α expression on the ability of tumor cells to adhere to MVEC and MVEC previously treated with 10U/mL of human recombinant IL-1β for 24 hours." (PMID 26460957, 2015). "VEGF-A, TNF-α and IL-1α were tested, all of which are known as key molecules that regulate angiogenesis via various mechanisms, especially in the tumor microenvironment." (PMID 26204526, 2015). "Nevertheless, IL-1α produced by tumor cells effectively increased their transmigration across the endothelium." (PMID 26460957, 2015). "Necroptotic cancer cells released interleukin-1α (IL-1α), which was required for powerful activation of dendritic cells (DC) to produce IL-12, a cytokine critical for anti-tumor responses." (PMID 25888634, 2015). "In this respect, IL-1α is a cytokine with DAMP-like properties that is released from dying tumor cells and binds the IL-1 receptor (IL-1R) on immune cells." (PMID 26307977, 2015). "We analyzed IL-1α production ex vivo by tumor samples from 35 patients (28.6%) included in the study, 10 of whom developed distant metastasis during the follow-up period." (PMID 26460957, 2015). "When IL-1α transcript-levels were combined with clinical factors related to tumor metastasis, the predictive power of the model increased significantly." (PMID 26460957, 2015). "Taken together, these findings show that IL-1α is an important factor in the crosstalk between tumoral cells and surrounding stroma and endothelial cells." (PMID 26460957, 2015). "Human BRAFV600E CM cell lines also induced the expression of IL-1α and IL-1β, which in turn induced COX-2 and PD ligand expression in tumor-associated fibroblasts, suppressing T cell function." (PMID 25709607, 2015). "IL-1α mRNA and protein secretion were higher in tumor samples from patients who later developed distant metastasis than in patients who did not." (PMID 26460957, 2015). "The co-injection of prostate cancer cell lines with IL-1α-treated MSCs promotes tumor growth in mice." (PMID 24502410, 2014). "In various tumor models, we found that IL-1β induces increased tumor growth, invasiveness, and angiogenesis, when compared to IL-1α." (PMID 24734023, 2014). "Their data suggested that producing sufficient levels of IL-1α in tumors initiates an immunostimulatory response to cancer cells and suppresses tumor growth at both treated and distant sites." (PMID 28548063, 2014). "Interleukin (IL)-1 signaling through its agonistic proteins IL-1α and IL-1β is involved in inflammatory responses, but also affects malignant processes including tumorigenesis, tumor invasiveness, and tumor-host interactions." (PMID 24901233, 2014). "On the other hand, some reports have demonstrated that IL-1α is served as a tumor promoter and poor prognosis factor in various tumors." (PMID 24924428, 2014). "Examination of anti-IL-1α treated tumors upon necropsy revealed an increase in tumor infiltrating CD4+ and CD8+ T cells and a decrease in the populations of both malignant LGLs and neutrophils." (PMID 24416335, 2014).
tumor (continued). "In IL-1α KO mice, tumor growth and angiogenesis in Matrigel plugs were observed to a lesser extent than in WT mice, but higher than those in IL-1β KO mice." (PMID 24734023, 2014). "Using IL-1 KO mice, we demonstrated that microenvironment-derived IL-1β, and to a much lesser extent IL-1α, is responsible for in vivo tumor angiogenesis and invasiveness of B16 melanoma cells." (PMID 24734023, 2014). "Host-derived IL-1α is also crucial in cancer immunosurveillance and in shaping the immunogenicity of malignant cells during the process of tumor progression." (PMID 28548063, 2014). "Prior studies have shown that a major agonist protein of the interleukin 1 family (i.e. IL-1α) is present in abundance in tumor microenvironment where it plays a major role in tumourigenesis." (PMID 25237386, 2014). "They showed that tumor cell- or host-derived IL-1β promoted tumor initiation, invasiveness, immunosuppression and angiogenesis while IL-1α preferentially activated anti-tumor cell immunity." (PMID 24924428, 2014). "Animal studies have further confirmed the role of IL-1α in tumor development and blood vessel growth." (PMID 25237386, 2014). "In these studies, IL-1α was shown to be involved in the induction of VEGF/VEGFR2 in the tumor microenvironment, through a cascade involving leptin/Notch." (PMID 24734023, 2014). "Angiogenic VEGF-A and lymphangiogenic VEGF-C and VEGF-D were up-regulated in the tumor stromal macrophages of highly metastatic tumors expressing IL-1α and/or IL-1β." (PMID 24924428, 2014). "IL-1α−/− immunogenic cells are rejected in intact mice by conventional innate and specific anti-tumor immune effector cells, including NK cells, as well as by CD4+ and CD8+ T cells." (PMID 23847618, 2013). "Tumor necrosis factor-alpha (TNF-α) and interleukin-1 alpha (IL-1α) are produced by macrophages, and they play an important role in tumor conditions." (PMID 24959547, 2013). "The inflammation in PDAC is to high extent driven by IL-1α, expressed and secreted by the tumor cells and affecting the stroma cells, i.e. CAFs, which produce massive amount of inflammatory and immune regulatory factors both in vitro and in vivo." (PMID 23951028, 2013). "The expression of IL-1α in 3-MCA-induced tumor cells from IL-1β KO mice concomitantly activated a strong T helper and CTL response, which also contributed to the reduced in vivo growth of these cells in WT mice." (PMID 23847618, 2013). "Tumor growth and cytokine responses (IL-1A, MCP-1, TNF-α) were observed for two weeks post-implantation." (PMID 23940596, 2013). "In their secreted form, IL-1α and IL-1β are involved in tumorigenesis and tumor invasiveness, whereas IL-1α, when expressed on the cell membrane, stimulates anti-tumor cell immunity." (PMID 24312101, 2013). "It was reported that MCP-1 favors tumor angiogenesis and early tumor growth by inducing TNFα, IL-1α, and VEGF by TAMs." (PMID 24377047, 2013). "IL-1α has previously been established as an important factor involved in the communication between tumor cells and CAFs in PDAC." (PMID 23951028, 2013). "IL-1α is expressed and secreted by the tumor cells and exerting its effect on the stroma, i.e. cancer associated fibroblasts (CAF), which in turn produce massive amount of inflammatory and immune regulatory factors." (PMID 23951028, 2013). "The decreased levels of IL-1α in PC013 cells exposed to p38MAPK inhibitor should reduce IL-1α autocrine feedback and modulate the functions such as tumor cell mobility." (PMID 23951028, 2013). "In such patients, one can envision initial systemic neutralization of IL-1β followed by application of IL-1α expressing tumor cell vaccines." (PMID 23847618, 2013). "Immunosuppression induced by IL-1β usually acts in a dominant manner and masks the immunostimulatory anti-tumor effects of IL-1α." (PMID 23847618, 2013).